IGFL3 (IGF like family member 3)
Description:
Potential ligand of the IGFLR1 cell membrane receptor.
Synonyms: UNQ483
Tractability: Antibody: UniProt places it where antibodies can reach, with high confidence; UniProt predicts a signal peptide or a membrane-spanning region; its Gene Ontology location is reachable by antibodies, with medium confidence.
Gene: Protein-coding gene on chromosome 19 (46,120,067 to 46,124,688, reverse strand). Ensembl gene ENSG00000188624.
Subcellular location: Secreted
Gene Ontology:
Molecular function: signaling receptor binding
Cellular component: extracellular region
Genetic constraint (gnomAD): Loss-of-function variants: 13 observed, 17.83 expected, observed/expected ratio (o/e) 0.73, 90% interval 0.47 to 1.16. The upper end of that interval is the gene's LOEUF score, 1.16, which puts it in group 5 of 6, group 1 being the genes least tolerant of losing a copy. Missense variants: 153 observed, 158.28 expected, observed/expected ratio (o/e) 0.97, 90% interval 0.85 to 1.11. Synonymous variants: 52 observed, 59.99 expected, observed/expected ratio (o/e) 0.87, 90% interval 0.69 to 1.09.
Homologues: Orthologues: chimpanzee IGFL3 (99% identical), macaque IGFL3 (80% identical). Paralogues in human: IGFL2 (54% identical), IGFL4 (44% identical), IGFL1 (37% identical).
Diseases named in the same sentence as IGFL3 in open-access papers:
IGFL3 is named in the same sentence as 4 diseases in open-access papers, as found by Europe PMC text mining. Sharing a sentence is not in itself a finding about the gene and the disease. The quoted sentences say what the papers report.
psoriasis (3 papers, 2021 to 2025). An autoimmune condition characterized by red, well-delineated plaques with silvery scales that are usually on the extensor surfaces and scalp. "As with Igfl3, increased expression of 2610528A11Rik and its human ortholog are linked to mouse models of skin wounding and psoriasis, human psoriasis, and human atopic dermatitis." (PMID 34445339, 2021). "Among them, the expression of Igfl3 is mainly limited to the skin, which can promote cell proliferation and inhibit psoriasis and atopic dermatitis." (PMID 41162173, 2025). "As with Igfl3 and 2610528A11Rik, studies suggest that Il1f6 (IL36α) plays an important role in both psoriasis and atopic dermatitis." (PMID 34445339, 2021).
breast carcinoma (1 paper, 2022). "IGFL3 is implicated in TFGβ signaling in breast cancer, but was not previously linked to UL until this study." (PMID 35740301, 2022).
tumor (2 papers, 2015 to 2022). "Epigenetic regulation of IGFL3 in UL through H3K27ac could lead to dysregulation of TGFβ3 pathway in this tumor." (PMID 35740301, 2022). "Other IGF family members with increased RNA message levels in this tumor (compared to muscle and bone) include IGFBPL1 (5-6-log2-fold), IGFL3 (6-7-log2-fold), and IGF2BP3 (2-6-log2-fold)." (PMID 25861239, 2015).
IGFL3 also shares sentences with these, for which no sentence is quoted: atopic dermatitis (2 papers).